PTH (parathyroid hormone)
Diseases named in the same sentence as PTH in open-access papers (continued):
Sharing a sentence is not in itself a finding about the gene and the disease.
hyperparathyroidism (continued). "Brown tumors are rare focal giant-cell lesions that arise as a direct result of the effect of parathyroid hormone on bone tissue in some patients with hyperparathyroidism." (PMID 19830212, 2009). "While in hyperparathyroidism PTH receptor is over stimulated by excess PTH, in FD the same receptor is inherently active owing to the mutation in the α subunit of the G protein." (PMID 19895712, 2009). "In our patient the PTH level was inappropriately normal, which cannot exclude coexisting hyperparathyroidism." (PMID 18652699, 2008). "Serum parathyroid hormone levels should be determined when calcium levels are at the upper limits of normal to exclude normocalcemic hyperparathyroidism." (PMID 21139759, 2007). "Therapies to increase serum calcium, decrease serum phosphate, and reduce PTH levels have resulted in decreased frequency and severity of hyperparathyroidism." (PMID 17622566, 2007). "The clinical manifestations of hyperparathyroidism are usually more severe, and serum levels of calcium, PTH and alkaline phosphatase are significantly higher than in patients with adenoma." (PMID 15975144, 2005). "The diagnosis of pHPT hinges on biochemical assessments, primarily elevated serum calcium and/or PTH levels, while other potential causes of hyperparathyroidism or hypercalcemia must be ruled out." (PMID 39820817, 2025). "We hypothesized that high baseline PTH levels contribute to more severe hyperparathyroidism during this period." (PMID 40525801, 2025). "In our small, single tertiary center cohort of pediatric patients with disorders of calcium metabolism, the most common condition was hypoparathyroidism (n = 7), followed by PTH resistance (n = 3), hyperparathyroidism (n = 1), calcipenic rickets (n = 1), and syndromic hypercalcemia (n = 1)." (PMID 41155848, 2025). "However, clinical evidence remains insufficient to support the routine use of PTH analogs in patients with overt hyperparathyroidism." (PMID 41517382, 2025). "However, 36 of 107 children (33.4%) had persistent hyperparathyroidism between 3 and 12 months post-transplant, and among these 36, 13 underwent testing at 2 years; 11 of them continued to show elevated PTH." (PMID 40451790, 2025). "The patient had elevated PTH levels despite normal serum calcium, and no secondary causes of hyperparathyroidism were identified." (PMID 40981138, 2025). "In addition, mild hyperparathyroidism was observed, even when the PTH levels were within the CKD-MBD parameters set by the Kidney Disease: Improving Global Outcomes organization." (PMID 39812596, 2025). "It is also unknown at this time as to when and at what level of PTH treatment of burosumab-induced hyperparathyroidism should be indicated." (PMID 40922882, 2025). "For instance, it may be used to regulate urate oxidase expression for gout treatment, or parathyroid hormone (PTH) for managing hyperparathyroidism, offering a flexible and responsive approach to precision medicine." (PMID 40619603, 2025). "On examining possible differences in functional performance and normal parathyroid function or hyperparathyroidism, differences were only observed in the mean SPPB score (8 ± 2.5 pg/mL in patients with normal PTH versus 7.2 ± 2.4 pg/mL in patients with hyperparathyroidism; p = 0.019)." (PMID 39860340, 2025). "This article reviews the skeletal involvement in the most frequent parathyroid disorders, hyperparathyroidism and hypoparathyroidism, and rare familial disorders of PTH metabolism, as assessed by clinical, laboratory, and imaging parameters, and the effect of the available treatment strategies." (PMID 40177730, 2025). "Notably, 21.5% of patients had elevated PTH ≥ 45 pg/mL: 186/246 (75%) had mild hyperparathyroidism (PTH ≥ 45 pg/mL) and 60/246 (25%) had overt hyperparathyroidism (PTH ≥ 65 pg/mL)." (PMID 40709988, 2025). "By definition, hyperparathyroidism is characterized by increased levels of PTH." (PMID 40177730, 2025).
hyperparathyroidism (continued). "Preliminary studies have shown that prolonged anti-FGF23 treatment may stimulate PTH secretion, thus leading to the development of hyperparathyroidism." (PMID 40297189, 2025). "Furthermore, long-term high PTH exposure in hyperparathyroidism significantly increases the number of remodeling sites." (PMID 40026929, 2025). "Hyperparathyroidism occurs commonly in the dialysis population, and surgical parathyroidectomy (PTx) is often required when medical therapy to suppress parathyroid hormone (PTH) fails." (PMID 40670910, 2025). "In this context, an animal model of CKD with hyperparathyroidism and hyperphosphatemia showed that daily teriparatide improved bone mineralization and volume, suggesting retained anabolic activity despite elevated endogenous PTH." (PMID 41517382, 2025). "In a randomized, double-blind, crossover study including 15 MEN1 patients with hyperparathyroidism, cinacalcet led to normalization of serum calcium, significant increase in serum phosphate, and reduction of PTH levels in all patients after 3 months of therapy." (PMID 40177730, 2025). "The exclusion of patients with elevated PTH due to anti-resorptive therapy may further refine the cohort of patients with normocalcaemic hyperparathyroidism of unknown aetiology and improve identification of individuals who warrant PA screening." (PMID 40608198, 2025). "The observation that elder Trpv5−/− mice demonstrate severely elevated serum PTH in contrast to young knockout mice may provide some explanation for the hyperparathyroidism seen in the proband." (PMID 38528055, 2024). "Our finding that PTH levels at 1 year post-transplant were associated with DCGF and mortality underscores the importance of closely monitoring patients after transplantation to provide adequate treatment for persistent or new-onset hyperparathyroidism." (PMID 38384325, 2024). "Parathyroid hormone (PTH) should be included to assess for hyperparathyroidism." (PMID 39301310, 2024). "Hyperparathyroidism was defined in the study group as PTH >400 pg/ml." (PMID 38681457, 2024). "Varied sex differences in PTH and hyperparathyroidism are reported in the literature." (PMID 38292595, 2024). "Similarly, the clinical trials also had varying exclusion criteria regarding high serum calcium and PTH levels, likely influencing the prevalence of hypercalcemic hyperparathyroidism that we observed." (PMID 39151033, 2024). "In addition to serum PTH levels, the state of hyperparathyroidism depends on a combination of clinical factors, such as: changes in calcium-phosphorus metabolism, vitamin D activity, nutritional and inflammatory status." (PMID 37955523, 2024). "However, the parathyroid hormone (PTH) levels were still higher in vegans compared to omnivores, despite the same prevalence of hyperparathyroidism in all groups." (PMID 38919395, 2024). "Regardless of the primary cause of hyperparathyroidism, the action of excess PTH is calcium and phosphorus release from the bone by osteoclastic resorption, leading to osteopenia." (PMID 39834923, 2024). "In addition, HPT-II occasionally develops into a hypercalcemic state and excessive PTH secretion, similar to the autonomous type of hyperparathyroidism known as HPT-III, in ESRD patients undergoing chronic HD and/or kidney transplant recipients." (PMID 39152506, 2024). "High levels of PTH in hyperparathyroidism suppress hematopoiesis." (PMID 38152136, 2023). "In addition to the typical target organs regulated by PTH, the links between metabolic and cardiac comorbidities and hyperparathyroidism are conflicting." (PMID 37424030, 2023). "The pro-resorptive effect of constantly elevated serum levels of PTH (e.g., during the development of hyperparathyroidism) was attributed to the stage-specific capacity of PTH to induce the expression of RANKL and inhibit OPG expression throughout osteoblast differentiation." (PMID 38117357, 2023).
hyperparathyroidism (continued). "Hyperparathyroidism (HPT) is a rare condition characterized by excessive secretion of PTH." (PMID 36998475, 2023). "GFD-related improvement of PTH levels seem strictly related to the reversal of mucosal lesions, as hyperparathyroidism persists both in patients with refractory CD and patients with a low compliance to GFD, and is associated with alterations of vitamin D metabolite levels." (PMID 36676999, 2023). "It’s necessary to distinguish: persistent hyperparathyroidism (development of high calcium and PTH values within 6 months of parathyroidectomy for incomplete resection) and recurrent hyperparathyroidism (development of high calcium and PTH values after 6 months of eucalcemia)." (PMID 36998475, 2023). "Hyperparathyroidism in a clinical setting can lead to an increase in resting energy expenditure and muscle wasting, and clinical and experimental studies have suggested that excess PTH leads to adipose tissue browning, explaining the reduction in muscle mass." (PMID 36839171, 2023). "Hyperparathyroidism was defined as parathyroid hormone (PTH) > 300 pg/mL." (PMID 38130747, 2023). "Another study investigated vitamin D, calcium, and PTH in adolescents with severe/very severe dysmenorrhea and found that 82.1% of the studied participants had normal serum Ca, 80.4% had normal alkaline phosphatase and 48.2% had hyperparathyroidism." (PMID 38406773, 2023). "For different PTH daily doses (D ∈ {10μg, 20μg, 30μg}), cellular responsiveness is computed exemplarily for healthy person and patients with idiopathic osteoporosis and hyperparathyroidism." (PMID 36996072, 2023). "Although the link between obesity and hyperparathyroidism is unclear, the current study hypothesized that excess PTH reduces the adipocyte lipolytic response to catecholamine by increasing calcium influx." (PMID 37424030, 2023). "It's defined by consistently normal total and ionised calcium levels with elevated parathyroid hormone in the absence of secondary causes of hyperparathyroidism in at least three consecutive times over a period of three to six months." (PMID 37779800, 2023). "PTH level immediately returned to the normal at 10 min postoperatively, and remained normal at 20 min, 4 h, 24 h, 1 month, 2 months, 3 months, 4 months, 7 months and 8 months postoperatively, suggesting the complete remission of hyperparathyroidism." (PMID 37795364, 2023). "According to their study, PTH levels at 4 weeks post-transplantation may serve as a marker for the occurrence of hypercalcemic hyperparathyroidism during the follow-up." (PMID 36672533, 2022). "Indeed, the higher the preoperative PTH concentration of the patient, the more severe is their hyperparathyroidism, and the greater their preoperative bone resorption." (PMID 36531501, 2022). "The half-life of PTH in the circulatory system is less than 5 min, therefore, serum PTH monitoring can be used intraoperatively to assess whether the source of hyperparathyroidism has been eliminated." (PMID 35987641, 2022). "However, intraoperative PTH monitoring showed an initial decrease to 203 pg/mL from a baseline of 443 pg/mL and a subsequent increase to 293 pg/mL suggesting the persistence of hyperparathyroidism." (PMID 36457632, 2022). "Furthermore, for the prevention of post-KTx hyperparathyroidism, active intervention for elevated PTH prior to KTx should be considered." (PMID 35710357, 2022). "In the IBD patient cohort, there were significant differences between PTH, phosphate, and bone markers, which implies that patients were at risk of hyperparathyroidism with or without corticosteroid treatment." (PMID 35887903, 2022). "Moreover, serum levels of sclerostin are negatively correlated with the levels of serum PTH in patients with hyperparathyroidism." (PMID 34427705, 2022).
hyperparathyroidism (continued). "HBS develops when serum PTH levels decrease suddenly, such as following parathyroidectomy for hyperparathyroidism, with a shift in bone metabolism from one of resorption to net formation, and an influx of minerals into the bone leading to lowering of serum calcium and phosphate levels." (PMID 35497370, 2022). "Intraoperative monitoring of serum PTH level is important to assess whether the source of hyperparathyroidism has been eliminated." (PMID 35987641, 2022). "Unfortunately, although early and recent research has linked hyperparathyroidism to affective and cognitive symptoms, parathyroid hormone levels have not yet gained sufficient attention in CKD patients with depression." (PMID 36012909, 2022). "Interestingly, considering the impact of PTH on the bone and kidney, it is suggested that hyperparathyroidism promotes weight gain by increasing intraadipocyte free calcium, thus blunting the lipolytic reaction to catecholamines." (PMID 35265372, 2022). "However, hyperparathyroidism is a disease characterized by excessive secretion of PTH, which is a common finding in CKD patients with renal failure." (PMID 34202416, 2021). "Hyperparathyroidism is a condition characterized by increased parathyroid hormone (PTH) secretion." (PMID 34868788, 2021). "However, the PTH dosage in our study was lower than in some previous ones, which observed an overall anabolic effect—making it unlikely that we mimicked hyperparathyroidism." (PMID 34440827, 2021). "Hypovitaminosis D does not determinedly affect occurrence of obesity induced hyperparathyroidism, given that the association between serum PTH and body fat mass is independent of vitamin D status." (PMID 34422722, 2021). "Moreover, TZD treatment reduces the PTH levels in patients with hyperparathyroidism, suggesting that the increased PTH levels are at least in part secondary to hypercalciuria." (PMID 34977081, 2021). "Indeed, patients displayed a relative hyperparathyroidism: PTH levels were within the normal range, but significantly higher in patients compared to controls." (PMID 33911128, 2021). "One of the most important bone metabolic alterations is represented by hyperparathyroidism; this condition could be a maladaptive response (persistent hyper-PTH) or a compensatory response (de novo hyper-PTH)." (PMID 33922902, 2021). "In our study, PTH negatively correlated with Ca levels (r = − 0.39, p < 0.01), but not with BTMs, thus excluding hyperparathyroidism as a cause of accelerated bone turnover in this patient cohort." (PMID 34182958, 2021). "Additionally, a reliable method of PTH measurement is key for the detection of patients with hyperparathyroidism along with successive follow-up monitoring of medical interventions." (PMID 33139830, 2020). "A persistently high PTH in the presence of high serum Ca suggests hyperparathyroidism, and a calcimimetic, such as cinacalcet, may be indicated." (PMID 31667620, 2020). "Hyperparathyroidism could be described as an endocrine disorder resulting from increased secretion of parathyroid hormone and is characterized by hypercalcemia due to increased mobilization of calcium from bone to circulation." (PMID 32695835, 2020). "The effects of elevated parathyroid hormone on the skeletally immature bone in the setting of sarcoma formation are currently not well understood without current description of adolescent hyperparathyroidism-associated sarcomas." (PMID 32440625, 2020). "Very less is understood regarding the impact of caffeine on PTH and its use in hyperparathyroidism." (PMID 32983662, 2020). "For example, hyperparathyroidism and hypoparathyroidism could induce the imbalance of calcium and phosphorus via influencing the levels of PTH." (PMID 33015068, 2020). "While most patients with parathyroid cancer present with functioning lesions and hyperparathyroidism, some may have normal parathyroid hormone (PTH) levels." (PMID 31708875, 2019).
hyperparathyroidism (continued). "The PTH-gradient method, which compares serum PTH concentrations between the grafted and the non-grafted forearms, was originally applied to examine the function of transplanted parathyroid glands in patients with hyperparathyroidism." (PMID 30704522, 2019). "Seven patients (26.9%) had baseline hyperparathyroidism (PTH > 65pg / mL)." (PMID 30735332, 2019). "A biphasic chronological time course is described for hyperparathyroidism; in the first sub-clinical phase PTH levels are elevated but serum Ca is normal, and this phase remains sub-clinical because PTH levels are rarely measured with normal serum calcium concentration." (PMID 31360455, 2019). "Serum PTH values in patients would have been helpful in confirming hyperparathyroidism." (PMID 31346567, 2019). "A high level of PTH reflects hyperparathyroidism, while low levels reflect hypoparathyroidism." (PMID 31687055, 2019). "The measurement of parathyroid hormone (PTH) is necessary for the diagnosis of hyperparathyroidism." (PMID 30916167, 2019). "The stronger association in prevalent patients may be owing to sustainable hyperparathyroidism with parathyroid hyperplasia which may induce vascular calcification and abnormal bone metabolism with the prolonged exposure of PTH to vascular and bone." (PMID 30290781, 2018). "In addition, hyperparathyroidism aggravates the inflammation status in HD, and PTH level is positively correlated with inflammation severity." (PMID 30149605, 2018). "While in the past surgery often represented the only way to correct a severe metabolic imbalance in the context of hyperparathyroidism, improvements in dialysis efficacy, and the new generations of drugs active on the Ca-Phosphate-PTH axis have sharply reduced the need for PTX." (PMID 29751781, 2018). "The main mechanisms involved in controlling bone regeneration and calcium homeostasis include changes in plasma PTH, calcitriol, calcium and phosphate, bone regeneration markers due to hypoparathyroidism and hyperparathyroidism, renal failure, daily PTH 1-34 administration, and RANKL inhibition." (PMID 30558600, 2018). "Hence, the present study aimed to assess the value of two assessment assays of iPTH and 1-84 PTH for predicting hyperparathyroidism secondary to chronic renal failure to recommend the assay with higher cost-effectiveness." (PMID 28975108, 2017). "These drugs are capable of making CaSR more sensitive to serum calcium levels, thereby decreasing the parathyroid hormone and the serum calcium in hyperparathyroidism, whether they are primary, secondary or neoplastic." (PMID 28122587, 2017). "We demonstrated the efficacy of cinacalcet in decreasing serum intact PTH level and calcium level and improving graft function in a patient with poorly-controlled severe hyperparathyroidism who developed early graft dysfunction from intratubular calcium deposition immediately after transplantation." (PMID 28390426, 2017). "Therefore, closely monitoring calcium and phosphorus levels, undergoing preventative treatment for hyperparathyroidism, and decreasing serum PTH levels, are essential ways to delay the progression of CKD and improve prognosis." (PMID 28741985, 2017). "In addition, while intraoperative PTH assessment is an effective method for confirming adequacy of treatment for hyperparathyroidism, only surgical pathology can confirm malignancy, which should be considered with PTH levels > 1,000." (PMID 28825015, 2017). "The role of normal maternal serum calcium levels perceived as being low by the newborn could promote the occurrence of this hyperparathyroidism, by stimulating PTH secretion, early during the intra-uterine life." (PMID 28122587, 2017). "This study found that PTH was positively associated with dialysis vintage; this is not an unusual finding since there are reports showing that hyperparathyroidism progresses with time on dialysis until the patient becomes older." (PMID 26808154, 2016).